CD80 (CD80 molecule)
Diseases named in the same sentence as CD80 in open-access papers (continued):
Sharing a sentence is not in itself a finding about the gene and the disease.
Cirrhosis (2 papers, 2019 to 2025). A chronic disorder of the liver in which liver tissue becomes scarred and is partially replaced by regenerative nodules and fibrotic tissue resulting in loss of liver function. "Ex vivo: Increased activation markers (HLA-DR and CD80) and intracytoplasmic TNFα expression in monocytes from cirrhosis (DC) compared to HC." (PMID 30804947, 2019).
co-infection (2 papers, 2021 to 2022). "We found a minor depletion of CD80+CD86+ cells following GAS infection (p = 0.1), whereas co-infection caused a significantly increased proportion of this population when compared to uninfected controls." (PMID 36365071, 2022). "In vitro co-infection of macrophages led to significantly elevated expression of TLR2 and CD80 compared to bacterial mono-infection, whereas CD163 and CD206 were downregulated." (PMID 36365071, 2022).
colon adenoma (2 papers, 2016 to 2021). An adenoma that arises from the colon. "Moreover, in colonic adenoma CD80 mRNA levels resulted inversely correlated to the number of methylated genes (τ = −0.43, p = 0.04)." (PMID 27377375, 2016).
colonic dysplasia (2 papers, 2015 to 2021). "Specifically, it was demonstrated that inhibition of CD80 signaling in vivo in a CAC mouse model significantly increased the frequency and size of high-grade dysplastic lesions, whereas restoration of CD80 expression decreased colonic dysplasia." (PMID 34884543, 2021).
Ewing sarcoma (2 papers, 2023 to 2025). A small round cell tumor that lacks morphologic, immunohistochemical, and electron microscopic evidence of neuroectodermal differentiation. "In studies on Ewing Sarcoma, the activation of CD99 in macrophages was shown to induce the secretion of characteristic chemokines such as IL1β, IL6, TNFα, and markers CD80 and CD86 by M1 macrophages." (PMID 41000385, 2025).
eye infection (2 papers, 2024). An infectious process affecting any part of the eye. "As proof-of-principle, in this study, we used CD80−/− mice, which lack the CD80 gene, and compared their phenotype with WT control mice following ocular infection with the virulent HSV-1 ocular strain of McKrae virus." (PMID 38376148, 2024). "We identified ICP22-mediated suppression of CD80 expression in dendritic cells as being central to delaying viral clearance and limiting the cytopathological response to primary eye infection." (PMID 38376148, 2024). "Out of 50 mice in the CD80−/−-infected group, 35 (70%) survived the ocular infection, whereas 34 of 39 (87%) mice in the WT-infected group survived the ocular infection." (PMID 38376148, 2024).
fertility disorders (2 papers, 2008 to 2022). "Significantly high expression of CD80 molecules on pDCs obtained from women with fertility disorders and on mDCs from fertile women was observed." (PMID 18828896, 2008). "In cervix of Chlamydia positive women with fertility disorders, significantly high (P < 0.05) numbers of pDCs were present with increased CD80 expression." (PMID 18828896, 2008). "On the other hand, CD80 expression on pDCs of women with fertility disorders showed significant correlation with both IL-12 and IFN-γ levels suggesting the role of CD80 activation in secretion of type 1 cytokines." (PMID 18828896, 2008). "β-estradiol levels were significantly higher in women having fertility disorders as compared to fertile women and have significant correlations (r = 0.65; P < 0.05) with pDCs numbers, CD80 expression, IL-6 levels and IFN-gamma levels in these women." (PMID 18828896, 2008). "In cervical mDCs of Chlamydia positive fertile women and on pDCs of Chlamydia positive women with fertility disorders, significantly high expression of CD80 was observed compared to the controls (P < 0.05)." (PMID 18828896, 2008). "We detected significantly high levels of estradiol in women with fertility disorders, which correlated significantly with pDC levels, CD80 expression and IL-6 and IFN-γ secretion." (PMID 18828896, 2008). "CD80 expression on pDCs from Chlamydia positive women with fertility disorders showed significant correlation with both IL-12 and IFN-γ levels (r = 0.73; P < 0.01 and r = 0.88; P = 0.001 respectively)." (PMID 18828896, 2008). "Estradiol levels further showed significant correlations with pDC numbers in women with fertility disorders (r = 0.65; P < 0.05), with CD80 expression (r = 0.74 and r = 0.58 for both Chlamydia positive women with or without fertility disorders respectively)." (PMID 18828896, 2008).
Fungal infection (2 papers, 2015 to 2022). "Fungal infection induces an immunosuppressive state, and in murine models CD80+ neutrophilic cells have been shown to be importantly involved in this process." (PMID 25771792, 2015).
gonorrhea (2 papers, 2024 to 2025). A common sexually transmitted bacterial infection caused by Neisseria gonorrhoeae. "To further assess the adjuvant effect of Polymyxin B MPs with bacterial vaccine candidates, we analyzed the expression of MHC I, MHC II, CD40, and CD80 on dendritic cells after exposure to microparticulate gonorrhea vaccine formulations." (PMID 41441698, 2025). "The dendritic cells showed a significantly higher expression of the costimulatory molecule CD80 when exposed to the ent—DPD microparticles in combination with the gonorrhea vaccine microparticles." (PMID 38399399, 2024). "The incorporation of MF59 as a combination adjuvant with the Polymyxin B formulation significantly increased CD80 expression in comparison to the Polymyxin-adjuvanted gonorrhea vaccine, whereas Alum did not." (PMID 41441698, 2025). "CD80 expression with Polymyxin B MPs was significantly lower than with MF59-adjuvanted gonorrhea vaccine but not significantly different from the Alum-adjuvanted gonorrhea vaccine." (PMID 41441698, 2025).
helminth infection (2 papers, 2014 to 2021). "Thus, a lack of detectable expression of MHC-II in many infiltrating myeloid cells, along with a low/diminished level of the costimulatory molecules, CD80, CD86 and OX40L, suggests a defect in the maturation of these cells in the CNS environment during helminth infection." (PMID 25013939, 2014). "In MS patients with helminth infections, there is a compensatory abundance of IL-10-producing B cells through a mechanism that is largely dependent on the Inducible T cell costimulator ligand (ICOSLG)-pathway and not on the CD40, CD80 or CD86 pathways." (PMID 34122439, 2021).
Hepatitis (2 papers, 2008 to 2019). Inflammation of the liver. "To assess whether the activation status of DCs was altered in the absence of CD160, we measured the levels of multiple ligands on DCs, including CD1d, CD40, CD80, CD95, PD-L1, and HVEM, during α-GalCer-induced hepatitis." (PMID 31332204, 2019).
histiocytic sarcoma (2 papers, 2024 to 2025). An aggressive malignant neoplasm with a poor response to therapy, usually presenting as stage III/IV disease. "CD80 and CD86 expressing cells were further quantified by in situ hybridization and compared with data from three cases of canine histiocytic sarcoma (HS), a malignant tumor variant originating from antigen-presenting interstitial dendritic cells." (PMID 39619201, 2024). "Thus, the present study aimed to investigate the effects of CD80 and CD86 in histiocytic sarcoma (HS), a rare and progressive malignancy in dogs and to elucidate the status of the interferon-I pathway." (PMID 40271486, 2025). "Finally, we tested the hypothesis whether canine histiocytic sarcoma (HS), a malignant canine tumor of interstitial DC origin that does not undergo regression but usually progresses with poor prognosis, lacks CD80 and CD86 expression." (PMID 39619201, 2024).
inflammatory bowel disease (2 papers, 2017 to 2019). A spectrum of small and large bowel inflammatory diseases of unknown etiology. "The DC surface receptor costimulatory molecules CD86, CD80, CD83, and CD40 generate important signals for stimulating naive T cell differentiation and may inhibit oral tolerance in not only IDDM but also inflammatory bowel disease (IBD) and multiple sclerosis." (PMID 28396662, 2017). "Moreover, IECs isolated from patients with inflammatory bowel disease (IBD) expressed MHC II, CD80 and CD86 and were found capable of inducing CD4 T cell proliferation and IFNγ secretion." (PMID 31316504, 2019).
inflammatory skin disease (2 papers, 2022 to 2025). Inflammatory skin disorders covers a broad category that includes many conditions ranging in severity, from mild itching to grave medical health complications These disorders are common in people of all ages and races. "Importantly, given the lack of CD86 and CD80 expression in KCs, our study indicates new therapeutic options for inflammatory skin diseases, targeting CD6 directly in the skin rather than using systemic routes." (PMID 36353616, 2022).
ischemic stroke (2 papers, 2014 to 2021). A stroke disorder caused by obstruction of blood flow to the brain, due to thrombotic (local blood clot formation) or embolic (due to a blood clot or other material traveling from another site) event. "We examined the subtype-specific distribution of the CD163+ and CD80+ circulating monocytes and evaluated their association with the inflammatory status in 26 ischemic stroke patients and 16 healthy controls." (PMID 34201498, 2021). "The present study was conducted to delineate the CD163 and CD80 profiles in the circulating monocytes of patients after an ischemic stroke and healthy individuals to provide information about their phenotypic distribution and putative function." (PMID 34201498, 2021). "Thus, it appeared as though the molecules of the CD80/CD28, CTLA-4, and the PD-1/PD-L pathway are more critical than others in ischemic stroke." (PMID 25157219, 2014).
juvenile idiopathic arthritis (2 papers, 2022 to 2024). Juvenile idiopathic arthritis (JIA) is the term used to describe a group of inflammatory articular disorders of unknown cause that begin before the age of 16 and last over 6 weeks. "To date, CTLA4 Ig (abatacept), which binds to CD80/CD86 and inhibits inflammatory T cell activation, has been approved by the US Food and Drug Administration to treat RA, juvenile idiopathic arthritis, and active psoriatic arthritis." (PMID 36271469, 2022).
latent infection (2 papers, 2024). "CD80 and CD86 interact on APC and CD28 on T cells as costimulatory signals for the activation of T cells, are key players in anti-viral humoral and cellular immune responses, and play a critical role in the control of chronic and latent infections." (PMID 38674902, 2024). "By evaluating the effects of CD80 activity on primary and latent infection, we found that in the absence of CD80, virus replication in the eyes and virus reactivation in latent trigeminal ganglia were both significantly reduced." (PMID 38376148, 2024).
leishmaniasis (2 papers, 2014 to 2016). Infectious disease that is transmitted through the bite of hematophagous female phlebotomine sand flies. "There are reports indicating down modulation of CD80 and 86 expression in certain diseases, including leishmaniasis." (PMID 27776125, 2016). "In a murine model of leishmaniasis a blockade of CD86 results in inhibition of Th2 cytokine secretion and enhancement of the Th1-type immune response, while a blockade of CD80 exerts the opposite effect." (PMID 24771983, 2014).
leukoplakia (2 papers, 2015 to 2023). A white patch or plaque on a mucous membrane that cannot be characterized clinically or pathologically as any other disease. "We examined the infiltration of macrophages for various pathological grades of leukoplakia using antibodies to CD68, CD80, and CD163." (PMID 26242181, 2015). "Using CD68 (pan-MΦ), CD80 (M1 MΦ), CD163 (M2 MΦ), and a simple binary model of macrophage phenotype (M1-CD80 versus M2-CD163), they could only observe a significant increase in CD163+ cells in dysplastic leukoplakias, while CD68 and CD80 remained the same." (PMID 37190121, 2023).
Lewis Lung Carcinoma (2 papers, 2010 to 2024). "In the Lewis lung carcinoma model, vaccination efficiently increases the CD3+CD4+ and CD3+CD8+ T cell populations in the spleens and CD3+CD8+, CD3−CD8+, and CD11b+CD80+ cell populations in the tumors, suggesting the alteration of tumor microenvironments from cold to hot tumors." (PMID 38932378, 2024). "In the Lewis lung carcinoma model, vaccination efficiently increases the CD3+CD4+ and CD3+CD8+ T cell populations in the spleens and CD3+CD8+, CD3−CD8+, and CD11b+CD80+ cell populations in the tumors, suggesting the alteration of the tumor microenvironment from cold to hot tumors." (PMID 38932378, 2024).
liver cancer (2 papers, 2020 to 2022). An epithelial or non-epithelial malignant neoplasm that arises from the liver. "The results showed that these genes were highly expressed in liver cancer including CD80, CD44, HAVCR2, NRP1, and LAIR1." (PMID 35067176, 2022).
liver disease (2 papers, 2016 to 2024). "To investigate the relative contribution of macrophages in liver diseases, we applied SPADE to CD45, CD11b, F4/80, CD163, CD80, and PD-L1 to compartmentalize macrophages." (PMID 38032223, 2024).
liver fibrosis (2 papers, 2016 to 2021). "Another hypothesis could be that PGE2, which is upregulated during HBV infection, is inhibiting CD80 upregulation, and supressing liver fibrosis and inflammation." (PMID 27348308, 2016). "Therefore the levels of liver fibrosis and inflammation might be correlated with CD80 expression on CD68+ cells because both phenomena are influenced by PGE2." (PMID 27348308, 2016). "Again, the yield of CD11c+CD80+, CD11c+CD86+cells did not vary between hepatic NPCs harvested from IDO1−/− fibrotic mice, or WT fibrotic mice and knock out of IDO1 did not influence the expression levels of CD80 and CD86 on hepatic CD11c+DCs during liver fibrosis induced by BDL." (PMID 33414436, 2021).
lung disease (2 papers, 2020 to 2026). "These include CD14, CD40, and CD80, which are surface receptors that trigger NF-κB activation, and IL-8, IL-6, and RANTES that are NF-κB-responsive cytokines with major roles in the pathogenesis of CF lung disease." (PMID 32528461, 2020).
measles (2 papers, 2024 to 2025). A highly contagious viral infection caused by the measles virus. "The CD80 expression was significantly higher with measles + Polymyxin B MPs than with measles + MF59 MPs and comparable to measles + Alum MPs." (PMID 41441698, 2025). "However, the cells exposed to n-butyl—DPD, isobutyl—DPD, n-hexyl—DPD, and phenyl—DPD microparticles showed significantly lower expression of the costimulatory molecule CD80 than the cells exposed to the marketed measles vaccine." (PMID 38399399, 2024).
mesothelioma (2 papers, 2018 to 2022). A usually malignant and aggressive neoplasm of the mesothelium which is often associated with exposure to asbestos. "In contrast, mesothelioma increased MHC-II+ and CD80+CD11c+ cells in TDLNs, relative to age-matched healthy LNs." (PMID 30560130, 2018).
oral cancer (2 papers, 2019 to 2024). "Upregulation of another immune checkpoint gene CD80, observed in oral cancer, was found to be driven by significant promoter hypomethylation in OSCC-GB patients." (PMID 31796082, 2019).
peanut allergy (2 papers, 2021 to 2025). "The study conducted by other researchers also reported similar results, showing that CD86 is an important factor in the induction of peanut allergy and the interaction between CD80 expression on DCs and CTLA-4 expression on T cells are both crucial for the induction of tolerance." (PMID 34177885, 2021). "In a peanut allergy model, animals treated with CTLA-4Ig, anti-CD86, or anti-CD80 plus anti-CD86 achieved successful oral tolerance, but those treated with anti-CD80 were compromised." (PMID 39950084, 2025).
Peri-Implantitis (2 papers, 2022). An inflammatory process with loss of supporting bone in the tissues surrounding functioning DENTAL IMPLANTS. "Peri-implantitis lesions showed a tendency towards a higher CD80/CD163 ratio than in healthy peri-implant mucosa with a borderline difference (p = 0.054)." (PMID 36286036, 2022). "A borderline significance (p = 0.054) was observed when the CD80/CD163 ratio was compared between peri-implantitis and healthy peri-implant tissue samples, the latter being lower." (PMID 36286036, 2022). "In the same line, an immunohistochemical analysis showed a significantly higher expression of M1 (CD80) inflammatory phenotype at advanced peri-implantitis sites." (PMID 36761175, 2022). "The CD80/CD163 ratio was also decreased in the peri-implantitis group but without a statistically significant difference." (PMID 36286036, 2022).
pituitary tumor (2 papers, 2021 to 2023). A benign or malignant neoplasm affecting the pituitary gland. "The increased expression of immune checkpoints, such as the programmed death ligand-1 (PD-L1) and the cytotoxic T-lymphocyte-associated protein 4 (CTLA-4) ligands CD80 and CD86, has been associated with aggressiveness in proliferative pituitary tumors." (PMID 37958702, 2023). "Furthermore, aggressive pituitary tumors demonstrated significantly higher levels of CD80 and CD86 compared to non-aggressive tumors." (PMID 34745002, 2021). "We found higher expression of PD-L2, CD80, and CD86 in aggressive pituitary adenomas when compared to normal pituitary tissues, suggesting the accumulation of peripheral immune cells like regulatory T cells, NK cells and dendritic cells in the pituitary tumor immune microenvironment (TIME)." (PMID 34745002, 2021).
preeclampsia (2 papers, 2020 to 2022). Preeclampsia is a hypertensive disorder of pregnancy that is characterized by new-onset hypertension with proteinuria presenting after 20 weeks of gestation, and depending on mild or severe forms may initially present with severe headache, visual disturbances, and hyperreflexia. "Another that DCs derived from the peripheral blood of preeclampsia patients expressed increased levels of CD80 and CD86." (PMID 36303229, 2022). "In other pregnancy complications, such as preeclampsia, peripheral DCs from patients express higher levels of both CD80 and CD86." (PMID 32265918, 2020).
pulmonary TB (2 papers, 2023). "However, DCs in active pulmonary tuberculosis patients expressed lower levels of HLA-DR and CD80 than those from healthy controls." (PMID 36977141, 2023). "Our study identified unique gene signatures (IL-27, STAT1, IRF1, TLR4, IL-15, IL-2RA, IL-24, TGFβ, CD28, CD80, NFATC1, and PTGDR2) that discriminate active pulmonary TB from uninfected controls using unstimulated PBMCs." (PMID 37460564, 2023).
rectal adenocarcinoma (2 papers, 2019 to 2020). "Moreover, the TCM from rectal adenocarcinoma significantly enhanced CD80 (p = 0.028), CD86 (p = 0.016) and CD83 (p = 0.002) compared to LPS-induction in background media alone, cRPMI (+)." (PMID 32552799, 2020). "However, we found a higher level of PD-L1, PD-L2, CD80, CD86, Tim-3, LAG3, and 4-1BB in EBV-positive STAD and cytomegalovirus-positive colon and rectum adenocarcinoma than in virus-negative tumor samples." (PMID 30911684, 2019).